AKT1 (AKT serine/threonine kinase 1)
Diseases named in the same sentence as AKT1 in open-access papers (continued):
Sharing a sentence is not in itself a finding about the gene and the disease.
lung adenocarcinoma (95 papers, 2009 to 2026). A carcinoma that arises from the lung and is characterized by the presence of malignant glandular epithelial cells. "The results of immunofluorescence and Co-IP indicated that the positive correlation of CA916798 expression with AKT1 activation might be associated with drug resistance of lung adenocarcinoma." (PMID 23667466, 2013). "The survival curve indicated that the expression of PIK3R1, PIK3CA, and AKT1 correlated with the mOS of lung adenocarcinoma (p < 0.05)." (PMID 36654811, 2023). "AKT1 expression was found to be high in normal alveolar cells but average in lung adenocarcinoma and squamous cell carcinoma." (PMID 36654811, 2023). "For instance, in lung adenocarcinoma, miR-520c-3p have a lower expression level and regulates its targets AKT1 and AKT2 expression." (PMID 36528556, 2022). "LINC00324 levels are markedly up-regulated in lung adenocarcinoma, and LINC00324 overexpression promotes the progression of lung adenocarcinoma through upregulation of Akt1 via sequestering miR-615-5p." (PMID 33318312, 2020). "Correlation analysis results showed that the expression of VEGFA, EGFR, CASP3, and AKT1 correlated with the median survival time of lung adenocarcinoma patients (P < 0.05)." (PMID 32148531, 2020). "Our studies have shown that the hub genes, such as VEGFA, EGFR, CASP3, and AKT1, as potential therapeutic targets of cinobufotalin injection correlated with the survival time of lung adenocarcinoma patients." (PMID 32148531, 2020). "LINC00324 can promote proliferation and metastasis but can inhibit cell apoptosis of lung adenocarcinoma cells by sponging miR-615-5p to promote AKT1 expression." (PMID 33193574, 2020). "The decrease in cell invasion due to the Akt1 knock-down is in agreement with another study reporting that silencing of Akt1 resulted in a moderate inhibition of A549 human lung adenocarcinoma cell invasion." (PMID 26234648, 2015). "AKT1 has been identified as a candidate driver gene in lung adenocarcinoma patients." (PMID 36949111, 2023). "For instance, upregulated expressions of Notch 1 in hypoxic lung adenocarcinoma cells activate insulin-like growth factor 1 receptor (IGF1R) via binding to the IGF1R promoter directly leading to activation of Akt1, which allows the tumor cells to survive under hypoxic parameters." (PMID 32316322, 2020). "This study suggests that compounds selectively targeting AKT1 may prove more effective than compounds that inhibit all three AKT isoforms at least in the treatment of lung adenocarcinoma." (PMID 26654940, 2016). "Similarly, it has been reported that silencing of Akt1 resulted in a moderate inhibition of A549 human lung adenocarcinoma cell proliferation and colony growth." (PMID 26234648, 2015). "A total of 1356 lung adenocarcinoma cases from April 2007 to May 2013 were sequenced for EGFR kinase domain mutations, KRAS mutations, HER2 kinase domain mutations, BRAF mutations, ALK fusions, ROS1 fusions, RET fusions and AKT1 mutations." (PMID 26486077, 2015). "Mutations that could be genuine but would require further investigation in a larger patient cohort are AKT1, FGFR1 and ERBB2, each occurring in 1/8 of the clinical samples and are reported as low frequency occurring mutations in lung adenocarcinoma by the COSMIC database." (PMID 23922754, 2013). "Lung adenocarcinoma cells are regulated by USP53, which deubiquitinates FKBP51, dephosphorylates AKT1, and controls glycolysis and apoptosis." (PMID 37894400, 2023). "In lung adenocarcinoma, LINC00324 knockdown restricts tumor cell growth and metastasis via regulation of the miR-615-5p–AKT1 axis." (PMID 32369777, 2020).
lung adenocarcinoma (continued). "NOTCH1 activates AKT-1 via PTEN repression and induction of the insulin-like growth factor 1 receptor (IGF-1R) in lung adenocarcinoma during hypoxia." (PMID 30087852, 2018). "The five largest node targets identified were protein kinase 1 (AKT1), STAT3, JUN, interleukin-6 (IL-6), and mitogen-activated protein kinase 3 (MAPK3), which may be important targets for the treatment of lung adenocarcinoma with QSFZYL." (PMID 40642092, 2025). "Mechanistically, ASK‐272aa competitively binds Akt1 with ASK1 and antagonizes the Akt1‐induced phosphorylation and inactivation of ASK1, thereby activating ASK1‐induced apoptosis, which in turn leads to reduced gefitinib resistance in lung adenocarcinoma cells." (PMID 37070530, 2023). "We present the first portrait of clinically actionable alterations in lung adenocarcinoma of Indian origin that includes EGFR, KRAS, EML4-ALK, AKT1, PIK3CA, FGFR4 and ERBB2, similar to that identified in other ethnic groups, and an additional subset of patients with FGFR3 mutations." (PMID 27998968, 2017).
pulmonary fibrosis (91 papers, 2009 to 2026). Chronic progressive interstitial lung disorder characterized by the replacement of the lung tissue by connective tissue, leading to progressive dyspnea, respiratory failure, or right heart failure. "AKT1 activation plays a crucial role in regulating pulmonary fibrosis, as it is strongly associated with the survival and differentiation of myofibroblasts." (PMID 37666859, 2023). "Akt1 was one of 3 related serine/threonine-protein kinases implicated in pulmonary fibrosis and lung injury and also played an essential role in immune cell modulation." (PMID 35227280, 2022). "It was reported that IL10, ARG1, and AKT1 were all associated with the macrophage activation and apoptosis in pulmonary fibrosis." (PMID 31105564, 2019). "In a hyperoxia-induced pulmonary fibrosis mice model, elevated CX3CR1 regulates macrophage autophagy and pulmonary fibrosis through the Akt1-signaling pathway." (PMID 39768150, 2024). "Akt1-mediated mitochondrial autophagy can promote the apoptotic resistance of alveolar macrophages and further aggravate pulmonary fibrosis." (PMID 38609879, 2024). "This AKT1-mediated mitophagy leads to apoptosis resistance and prolonged survival of macrophages, which are necessary for pulmonary fibrosis progression." (PMID 37666859, 2023). "The results revealed a significant increase in the expression of p-PI3K and p-Akt1 in the lung tissues of pulmonary fibrosis mice." (PMID 37781713, 2023). "Recently, Akt1-mediated ROS production and mitophagy contributes to alveolar macrophage apoptosis resistance and is required for pulmonary fibrosis." (PMID 33567502, 2021). "According to previous studies, Akt1-mediated mitophages contribute to alveolar macrophage apoptosis resistance, which is required for pulmonary fibrosis development." (PMID 31527305, 2019). "AKT1 plays a crucial role in positively regulating the anti-apoptotic process of alveolar macrophages, which is widely recognized as essential for the pathogenesis of pulmonary fibrosis." (PMID 39479511, 2024). "AKT1 induces mitochondrial ROS production and mitophagy in macrophages; subsequently, AKT1-mediated mitophagy can then increase resistance to alveolar macrophage apoptosis and pulmonary fibrosis." (PMID 38659590, 2024). "A network pharmacology analysis suggested that Lianhua Qingwen capsules might potentially treat and prevent COVID-19 by targeting the serine/threonine protein kinase (Akt1), which is involved in viral infection, lung injury, and lung fibrosis." (PMID 36846053, 2023). "The function of AKT1 in the progression of pulmonary fibrosis is closely related to TGF-β." (PMID 37666859, 2023). "protein–protein interaction protein interaction network analysis showed that PIK3CA, PIK3R1, MAPK1, SRC, AKT1, and so on may be the core targets of the compound Hongjingshen recipe in the treatment of pulmonary fibrosis." (PMID 36595795, 2022). "In addition, Akt1-mediated mitophagy contributed to apoptosis resistance of alveolar macrophages and was responsible for pulmonary fibrosis." (PMID 36430467, 2022). "In addition, previous studies also demonstrated that Akt1 suppressed cell apoptosis, induced mitochondrial ROS and mitophagy in macrophages and promoted lung fibrosis." (PMID 32724454, 2020). "ARG1 could regulate the macrophage phenotype transition and Akt1-mediated mitophagy contributed to alveolar macrophage apoptosis resistance and was required for pulmonary fibrosis development." (PMID 31105564, 2019). "Furthermore, a very recent study implicates AKT1 activation in the production of TGF-b by alveolar macrophages in the context of pulmonary fibrosis." (PMID 27769060, 2016).
pulmonary fibrosis (continued). "While there are three isoforms (AKT1, AKT2, and AKT3), researches related to pulmonary fibrosis have predominantly focused on the AKT1 and AKT2 isoforms." (PMID 39479511, 2024). "In idiopathic pulmonary fibrosis (IPF), the activation of AKT1 in alveolar macrophages is required for the development of pulmonary fibrosis." (PMID 39013891, 2024). "Study showed that mitophagy, which is modulated by Akt1 activation, contributes to alveolar macrophage apoptosis resistance and is required for macrophage-derived TGF-β1 expression in the development of pulmonary fibrosis." (PMID 29112159, 2017). "In this sense, the present study evaluated the histopathological features and immunohistochemical biomarkers (ACE-2, AKT-1, Caveolin-1, CD44v6, IL-4, MMP-9, α-SMA, Sphingosine-1, and TGF-β1 tissue expression) involved in the TGF-β1 signaling pathways and pulmonary fibrosis." (PMID 35008594, 2021). "The Akt1–mediated mitophagy induction contributes to apoptosis resistance of AMs, enables the expression of macrophage–derived TGF-β1, and ultimately promotes fibroblast differentiation and progression of pulmonary fibrosis." (PMID 30717487, 2019).
liver fibrosis (86 papers, 2014 to 2026). "Further investigation showed that PZH ameliorates liver fibrosis by modulating key targets, including AKT1, EGFR, and STAT3." (PMID 41181146, 2025). "Subsequently, celastrol administration significantly ameliorated hepatitis and liver fibrosis by reducing AKT1 and PI3K phosphorylation in both acute liver injury and chronic models of autoimmune hepatitis." (PMID 35359864, 2022). "Another study confirmed that TIM-4 in macrophages mediates the production of mitochondrial ROS via Akt1 pathway, and resulting in mitophagy during liver fibrosis." (PMID 35990621, 2022). "A PPI network showed that as hub and core targets, SRC, PIK3R1, STAT3 and AKT1 were potential anti-liver fibrosis targets of RGGs." (PMID 35115923, 2021). "Meanwhile, much evidence has confirmed that PIK3R1, STAT3 and AKT1 can regulate crucial cellular processes, including proliferation, survival, growth, autophagy, and metabolism, and improve liver fibrosis." (PMID 35115923, 2021). "Another research also suggested that the inhibition of AKT1-mediated ROS production suppressed the process of NAFLD to liver fibrosis conversion." (PMID 32863886, 2020). "The present studies showed the influences of SREBP1c on both receptors for TGFβ1 and PDGFβ, the most important cytokines for inducing HSC activation and liver fibrosis, and on their downstream signalling pathways of Smad3 and Akt1/2/3 in HSCs." (PMID 32678475, 2020). "Our data have shown that TIM‐4 regulation in KCs is associated with Akt1‐mediated mitophagy, which is required for KC‐derived TGF‐β1 expression during liver fibrosis." (PMID 31755616, 2020). "Together, these results indicate that both Akt1 and Akt2 are involved in ethanol and LPS-mediated hepatic fibrosis." (PMID 31671832, 2019). "From small molecule compounds targeting caspase-1 and Akt-1, compound 13 was selected for virtual screening with molecular modeling, molecular docking and MD simulations, for its effect of hepatic fibrosis." (PMID 26389883, 2015). "Then, module analysis of the 113 key OGEs was performed using MCODE and the CytoNCA plugin to obtain 6 core genes (CXCL8, MAPK1, AKT1, SRC, VEGFA, and IL-6), which might play important roles in the effects of JQH against WD-associated liver fibrosis." (PMID 35707473, 2022). "Moreover, there were 192 potential targets regulated by DSLHG, of which 86 were related to liver fibrosis, including AKT1, EGFR, and IGF1R." (PMID 31354851, 2019). "Based on these predictions, we selected PIK3CA, AKT1, HIF1A, VEGFA, and other related targets as the candidate targets of saffron for anti-hepatic fibrosis and conducted further experimental validation." (PMID 37959658, 2023). "Further investigation into the mechanisms by which SREBP1c regulates HSCs and liver fibrosis demonstrated that overexpression of SREBP1c inhibited liver fibrosis in mice by reducing the levels of TGFβ1 and signaling via SMAD3 and Akt1/2/3." (PMID 38137501, 2023). "Considering core targets of the PPI network and a network of the common targets and pathways enriched, AKT1, MAPK1, EGFR, MTOR, and SRC may be the core potential targets of CL against hepatic fibrosis." (PMID 37478207, 2023).
liver fibrosis (continued). "Considering the main targets showed by PPI network, we speculate that AKT1, MAPK1, EGFR, MTOR, and SRC may be the core potential targets of CL against hepatic fibrosis, and molecular docking was further performed." (PMID 37478207, 2023). "Hence, we thought that RGGs presented anti-liver fibrosis activity by regulating the expression of SRC, PIK3R1, STAT3, AKT1 and other core targets." (PMID 35115923, 2021). "However, TIM‐4 interference in the KCs inhibited Akt1‐mediated ROS production, resulting in the suppression of PINK1, Parkin and LC3‐II/I activation and the reduction of TGF‐β1 secretion during liver fibrosis." (PMID 31755616, 2020). "Furthermore, studies highlighting the mechanisms by which SREBP1c regulates hepatic stellate cells and liver fibrosis have revealed that the overexpression of SREBP1c inhibits liver fibrosis in mice by reducing TGF-β levels and signaling through SMAD3 and AKT1, AKT2, and AKT3." (PMID 38256181, 2024).
Alzheimer disease (83 papers, 2009 to 2026). A progressive, neurodegenerative disease characterized by loss of function and death of nerve cells in several areas of the brain leading to loss of cognitive function such as memory and language. "A previous study indicated that AKT1 polymorphisms might be associated with the risk of Alzheimer's disease in patients with T2DM." (PMID 38204223, 2025). "Interestingly, conditional inactivation of AKT1 has been linked to the hyperphosphorylation of TAU protein which is implicated in Alzheimer’s disease." (PMID 30956902, 2019). "Insufficient activity of the kinase Akt1 can lead to neuronal death, and it is one of the important proteins involved in the neuroinflammatory response of Alzheimer’s disease." (PMID 38039290, 2023). "Studies have shown that hippocampal long-term potentiation (LTP) was significantly inhibited in an animal model of Alzheimer's disease and that this inhibition is closely related to Akt1." (PMID 32461997, 2020). "This study investigated the regulatory role of the long non-coding RNA maternally expressed gene 3 (MEG3) in tau hyperphosphorylation and insulin signaling (PI3K/AKT1/GSK3β) under high-glucose (HG)-induced neurotoxic conditions mimicking Alzheimer’s disease pathology." (PMID 40869265, 2025). "Interestingly, AKT1, MAPK8, BCL2L1, FOXO3, and CTNNB1 were not only significantly associated with pathogenic genes (APP, MAPT, and PSEN2) but also with longevity in Alzheimer’s Disease." (PMID 36620771, 2022). "Akt1 as well as its downstream molecules offer great promise for the development of therapeutics against a number of neurological disorders such as stroke, spinal cord injury and neurodegenerative diseases such as Alzheimer disease, Parkinson disease and ALS." (PMID 19440551, 2009). "When applied to the four NDs Alzheimer's disease (AD), Huntington's disease, and spinocerebellar ataxia types 1 and 3, we predicted multiple members of the insulin pathway, including PDK1, Akt1, InR, and sgg (GSK‐3β), as common modifiers." (PMID 37984409, 2023). "In the Alzheimer’s disease pathway which contained 30 MFS-AD-treating targets, more targets were related to protease and serine/threonine–protein kinase, including two core targets, AKT1 and MAPK3." (PMID 36712676, 2022). "Indeed, p97/Gab2 is required for the PI3K/AKT1 signaling pathway and p97/Gab2-mediated PI3K/AKT1 activation is involved in the pathogenesis of Alzheimer’s disease (AD) that shows the reduced GRIA1 surface expression." (PMID 32781725, 2020). "While AKT1 and PPARGC1A are not brain-exclusive genes, RNA expression data from the Human Protein Atlas (HPA) confirm their widespread expression across key regions of the human brain, including the hippocampus and cortex—areas central to Alzheimer’s disease pathology." (PMID 40642087, 2025).